ENSG00000252691
Synonyms: LOC124900433
Gene: Small Cajal body-specific RNA gene on chromosome 1 (26,006,216 to 26,006,299, forward strand). Ensembl gene ENSG00000252691.
Gene Ontology:
Biological process: RNA processing
Cellular component: Cajal body; nucleolus